WNT4 (Wnt family member 4)
Diseases named in the same sentence as WNT4 in open-access papers (continued):
Sharing a sentence is not in itself a finding about the gene and the disease.
ovarian dysfunction (2 papers, 2014 to 2019). The inability of the ovaries to function. "Other genes like the WNT4, ESR2 and SF-1 have a necessary role for ovarian and testicular development function as demonstrated by the fact that genetic variants in these genes cause gonadal dysgenesis in 46,XY individuals, with ovarian failure in women and ovotesticular DSD42,70,74." (PMID 31745224, 2019).
prostate adenocarcinoma (2 papers, 2021 to 2023). "In order to evaluate the contribution of WNT4/TCF7L1 to the malignant progression of human prostate adenocarcinomas, AR-positive C4-2 and LNCaP cells stably expressing TCF7L1 were treated with the WNT4 protein." (PMID 34799554, 2021). "LTL331 xenografts exhibiting a classic prostate adenocarcinoma phenotype were transformed into castration‐resistant NEPC LTL331R tumours, during which Wnt9A and Wnt4 was markedly upregulated." (PMID 37771187, 2023).
prostate carcinoma (2 papers, 2021 to 2023). A carcinoma that arises from epithelial cells of the prostate gland. "WNT4 located in 1p36 and the induction of WNT4/TCF7L1 resulted in increased malignancy in prostate cancer that was linked to dysregulation of androgen receptor signalling and activation of the IL‐8/CXCR2 pathway." (PMID 37378426, 2023). "ADT induced the secretion of WNT4 which upon engagement of TCF7L1 in prostate cancer cells, enhanced IL-8 and CXCR2 expressions." (PMID 34799554, 2021). "Our results suggest that induction of WNT4/TCF7L1 results in increased NED and malignancy in prostate cancer that is linked to dysregulation of androgen receptor signaling and activation of the IL-8/CXCR2 pathway." (PMID 34799554, 2021).
pulpitis (2 papers, 2023 to 2025). Inflammation of the dental pulp. "Alterations in the Wnt4 signalling pathway are associated with various dental diseases, such as pulpitis, and further research on this signalling pathway could lead to new therapies for treating these conditions." (PMID 37512935, 2023). "Therefore, we hypothesized that ATF3 positively regulates WNT4 and inhibits the progression of pulpitis." (PMID 39801194, 2025). "In the present study, we found for the first time that the activating transcription factor ATF3 was aberrantly expressed in pulpitis and that the ATF3/WNT4 axis promoted the osteogenic differentiation of pulp stem cells by modulating the polarization and inflammatory response of M2 macrophages." (PMID 39801194, 2025).
Wilms tumor (2 papers, 2017 to 2023). An embryonal neoplasm characterized by the presence of epithelial, mesenchymal, and blastema components. "In this study, we investigated the impact of deleting the chromatin remodeling factor Smarca4 (Brg1), a human Wilms tumor-associated gene, in Wnt4-expressing cells." (PMID 37727504, 2023). "We have shown that, for example, Wilms tumor inhibits Wnt4 function and promotes kidney tumorigenesis." (PMID 29084770, 2017).
acne (1 paper, 2014). An inflammatory process of the sebaceous glands which is characterized by comedones, nodules, papules and/or pustules on the skin. "The WNT4 mutation has been reported to be associated with failure of müllerian duct formation and virilization, including acne, in at least four 46,XX women." (PMID 24641817, 2014).
adenoma (1 paper, 2021). A neoplasm arising from the epithelium. "Furthermore, RT-qPCR analysis for 19 members of the Wnt family indicated that only two family members, Wnt3 and Wnt4, had reduced expression in adenomas from PCdel mice." (PMID 33372038, 2021).
anaplastic thyroid carcinomas (1 paper, 2013). "It has been reported that WNT4 is poorly expressed in endometrial and squamous cell carcinomas; additionally, it has been observed that WNT4 is downregulated in human anaplastic thyroid carcinomas." (PMID 24274766, 2013).
and Gynecologic Cancers (1 paper, 2024). "In ILC, WNT4 is co-opted by estrogen receptor α (ER) via genomic binding in WNT4 intron 1, while in gynecologic cancers, a common genetic polymorphism (rs3820282) at this ER binding site alters WNT4 regulation." (PMID 38112643, 2024). "WNT4 regulates breast and gynecologic cancer metabolism via a previously unappreciated intracellular signaling mechanism at the mitochondria, with WNT4 mediating metabolic remodeling favoring lipid metabolism." (PMID 38112643, 2024). "WNT4 regulates breast and gynecologic cancer metabolism via a previously unappreciated intracellular signaling mechanism at the mitochondria, with WNT4 mediating metabolic remodeling." (PMID 38112643, 2024). "Understanding how WNT4 signaling is dysregulated, by estrogen and genetic polymorphism in ILC vs. gynecologic cancers, offers new opportunities for defining tumor biology, precision therapeutics, and personalized cancer risk assessment." (PMID 38112643, 2024). "We next examined rs3820282 genotype as a convergent mechanism of activating WNT4 signaling, paralleling ER regulation of WNT4 signaling in ILC, and based on the increased risk of gynecologic cancer associated with rs3820282 variant genotype, we expanded our studies into related models." (PMID 38112643, 2024). "Taken together, atypical intracellular WNT4 signaling, in part via genetic dysregulation, regulates the distinct metabolic phenotypes of ILC and gynecologic cancers." (PMID 38112643, 2024). "These analyses corroborate a previously unappreciated role for WNT4 in regulating cellular respiration, in lipid and amino acid metabolism, and in metabolic remodeling of ILC and gynecologic cancers." (PMID 38112643, 2024). "WNT4 signaling may integrate hormonal and/or microenvironmental signals to regulate metabolism in both ILC and gynecologic cancers." (PMID 38112643, 2024).
cataract (1 paper, 2018). Partial or complete opacity of the crystalline lens of one or both eyes that decreases visual acuity and eventually results in blindness. "Additionally, the mRNA of Wnt ligands was assayed by RT-qPCR, and Wnt4 and Wnt5a ligands were upregulated in K14E6 cataracts, whereas Wnt1, 3a, 7a, and 8a, were downregulated." (PMID 29888254, 2018).
chronic obstructive pulmonary disease (1 paper, 2019). A chronic and progressive lung disorder characterized by the loss of elasticity of the bronchial tree and the air sacs, destruction of the air sacs wall, thickening of the bronchial wall, and mucous accumulation in the bronchial tree. "In HAECs from individuals with chronic obstructive pulmonary disease, WNT4 upregulation increases IL8 and CXCL8 gene expression." (PMID 31558434, 2019).
cocaine addiction (1 paper, 2017). "In the present study, we found both Wnt4 and Notch2 expression increased 2 h after withdrawal and their roles in cocaine addiction should be further investigated." (PMID 28386228, 2017).
colonic diverticulosis (1 paper, 2019). "The top SNP associated with right-sided colonic diverticulosis was rs22538787, located near the WNT4 gene [combined set, P-value = 3.128 × 10−6, odds ratio = 1.415 (95% confidence interval: 1.223–1.637)]." (PMID 31089239, 2019).
cryptorchidism (1 paper, 2025). The failure of one or both testes of a male fetus to descend from the abdomen into the scrotum during the late part of pregnancy. "Copy number gain or gain of function of the WNT4 gene in humans results in varying degrees of 46, XY DSD, with clinical manifestations ranging from severe complete gonadal dysgenesis to mild phenotypes including hypospadias, cryptorchidism, and micropenis." (PMID 39773765, 2025).
cyst (1 paper, 2021). A sac-like closed membranous structure that may be empty or contain fluid or amorphous material. "We identify cyst cells (clusters 7 and 8) which express tj and wnt4 at high levels." (PMID 34824217, 2021).
depression (1 paper, 2017). "The canonical Wnt4 pathway induces inhibitory GSK3 phosphorylation, ultimately inducing hyperactivity and alleviating depression in the offspring." (PMID 28779169, 2017).
Distichiasis (1 paper, 2023). Double rows of eyelashes. "While the pathogenesis of distichiasis remains unclear, mutations have been shown to interfere with the interaction of the FOXC2 protein with the Wnt4 promoter, which has been hypothesized to result in abnormal signaling from the Wnt4-Frizzled-RYK signaling pathway." (PMID 37521194, 2023).
dyslipidemia (1 paper, 2022). "Exome-wide association studies (EWASs) identified eight SNPs related to the dyslipidemia-dominant subtype with genome-wide significance, which were located in the genes APOA5, BUD13, ZNF259, and WNT4." (PMID 36551856, 2022).
fibrosarcoma (1 paper, 2024). A malignant mesenchymal fibroblastic neoplasm affecting the soft tissue and bone. "We expressed WNT4 or WNT3A fused to C-terminal BirA biotin ligase in HT1080 WT and porcupine O-acetyltransferase (PORCN)-knockout (PKO) cells (Wnt-responsive fibrosarcoma cell line), and ILC cell line MDA MB 134VI (MM134)." (PMID 38112643, 2024).
glioblastoma (1 paper, 2024). The most malignant astrocytic tumor (WHO grade IV). "WNT4 and FRZB are two proteins involved in the Wnt signaling pathway, which regulates key cellular events during the development of the brain and is involved in the genesis of glioblastoma." (PMID 38612588, 2024).
HCMV infection (1 paper, 2010). "Interestingly, expression of Snail and wnt4 are rapidly down regulated during HCMV infection." (PMID 20585571, 2010).
head and neck squamous cell carcinoma (1 paper, 2018). A squamous cell carcinoma that arises from any of the following anatomic sites: lip and oral cavity, nasal cavity, paranasal sinuses, pharynx, larynx, and salivary glands. "DACT, WNT5A, and WNT7B were significantly positive correlation with TET1(p < 0.05), and WNT4 and WNT7A were negative correlation with TET1 in the TCGA Head and Neck Squamous cell Carcinoma database (p < 0.05)." (PMID 30075814, 2018).
hypothyroidism (1 paper, 2025). Abnormally low levels of thyroid hormone. "Additionally, hypothyroidism led to reduced uterine gene expression of LIF, BMP2, WNT4, and HAND2." (PMID 39859259, 2025).
inflammatory bowel disease (1 paper, 2025). A spectrum of small and large bowel inflammatory diseases of unknown etiology. "Variants in ZBTB40 have been associated with inflammatory bowel disease and low bone density and WNT4 with sex-determination developmental disorders." (PMID 39844285, 2025).
injury (1 paper, 2016). Damage inflicted on the body as the direct or indirect result of an external force, with or without disruption of structural continuity. "In conclusion, this is the first demonstration that increases in both kidney and urinary Wnt4 expression can be detected more sensitively and earlier than serum creatinine after kidney injury." (PMID 27600466, 2016). "In addition, we need to investigate whether urinary Wnt4 can serve as a noninvasive efficacy biomarker for evaluating the extent of kidney injury and to predict outcomes." (PMID 27600466, 2016).
liver disorder (1 paper, 2024). A disease involving the liver. "It has been reported that inhibition of the Wnt-4/β-catenin signaling pathway could be potential therapeutic targets in liver disorders." (PMID 39687571, 2024).
metastatic diseases (1 paper, 2021). "Patients with suspected metastatic diseases had higher Wnt-4 expression." (PMID 34945091, 2021). "Patients with suspected metastatic disease had higher mean Wnt-4 expression (1.5 vs. 1.1) compared with patients without metastases, but without significant differences between them (p = 0.104)." (PMID 34945091, 2021). "In our patients with suspected metastatic diseases, there was increased Wnt-4 expression, and, although this was not statistically significant, it suggests that ccRCC preserves this pathway for further development." (PMID 34945091, 2021).
minimal change disease (1 paper, 2016). "Both kidney and urinary Wnt4 expression were significantly increased in patients diagnosed with biopsy-proven minimal change disease (MCD) with tubular injury, all of whom nevertheless had normal estimated glomerular filtration rate (eGFR) and serum creatinine." (PMID 27600466, 2016). "Thus, we investigated Wnt4 expression in a mouse model of IRI and in patients with a normal estimated glomerular filtration rate (eGFR) who were diagnosed with biopsy-proven minimal change disease (MCD) with or without tubular injury." (PMID 27600466, 2016).
myeloma (1 paper, 2010). "The five remaining genes (NRG2, Wnt4, Wnt11, Wnt16 and FGF18) were considered as a "myeloma MGF" although they were not statistically significantly overexpressed in MMC compared to environment cell populations." (PMID 20465808, 2010).
Nephronophthisis 7 (1 paper, 2020). "There is also evidence that the transcription factor GLIS2 regulates Wnt4 expression, with homozygous mutant GLIS2-/- mice and GLIS2-knockdown IMDC3 cells showing upregulated Wnt4 expression and GLIS2 mutations linked to Nephronophthisis 7 in humans and mice." (PMID 32365994, 2020).
penile squamous cell carcinoma (1 paper, 2015). "Our results provide first evidence that WNT4 mediated Wnt signaling may be involved in penile squamous cell carcinoma." (PMID 25901368, 2015).
pituitary tumor (1 paper, 2023). A benign or malignant neoplasm affecting the pituitary gland. "Alternatively, Wnt4 has been reported to be overexpressed in pituitary tumors." (PMID 36965619, 2023).
preeclampsia (1 paper, 2021). Preeclampsia is a hypertensive disorder of pregnancy that is characterized by new-onset hypertension with proteinuria presenting after 20 weeks of gestation, and depending on mild or severe forms may initially present with severe headache, visual disturbances, and hyperreflexia. "WNT4 deficiency is likely involved in the occurrence of preeclampsia." (PMID 34642299, 2021). "Second, WNT4 protein in the decidual tissues of women with severe preeclampsia is significantly lower than that in normal pregnant women." (PMID 34642299, 2021). "WNT4 is also necessary for decidual cell differentiation and decidualization, which plays an important role in preeclampsia." (PMID 34642299, 2021).
premature ovarian failure (1 paper, 2011). "We sequenced the coding region and splice sites of WNT4 in 145 Han Chinese women with premature ovarian failure (POF) and 200 healthy controls." (PMID 21624127, 2011).
prostatic intraepithelial neoplasia (1 paper, 2015). "This was observed in a mouse model of prostatic intraepithelial neoplasia, where overexpression of Hmga2 in cancer-associated fibroblasts enhances expression of the Wnt ligands Wnt2, Wnt4, and Wnt9b, concomitant with enhanced Wnt signaling and nuclear β-catenin in adjacent neoplastic epithelium." (PMID 26244988, 2015).
retinal telangiectasia (1 paper, 2022). "Consistent with previous reports indicating the role of the WNT/β catenin signalling pathway in FSHD muscle phenotype but also retinal telangiectasia, we noticed a specific dysregulation of WNT4 and associated SFRP proteins in FSHD." (PMID 34859613, 2022).
serous carcinoma (1 paper, 2023). "At the same time, a cohort analysis utilizing the cBioPortal platform indicates that WNT4 might be significant for the growth of various histological tumor types as among a large group of EC patients, an alteration in WNT4 expression was found to be evident within the serous carcinoma." (PMID 37835474, 2023).
serous ovarian cancer (1 paper, 2020). "Parallel pathways associated with WNT4 were also identified in serous ovarian cancer, suggesting that WNT4 signaling is important in multiple tumor types." (PMID 33053661, 2020).
State anxiety (1 paper, 2013). "State anxiety assessed two months before the examination was positively and negatively correlated with miR-16 and its target WNT4 mRNA levels, respectively." (PMID 24130753, 2013).
testicular teratoma (1 paper, 2022). "To determine the effect of the MAP3K1R186G variant on kinase and ovarian-specific pathways, we evaluated phosphorylation levels of p38 and GSK3β as well as activation of the Wnt4/β-catenin pathway in the testicular teratoma cells (NT2/D1) and ovary-derived granular cells (KGN)." (PMID 35309143, 2022).
thymic atrophy (1 paper, 2021). "Wnt4-transgenic TEC-derived exosomes demonstrated the ability to delay age-related thymic atrophy." (PMID 34113341, 2021).
thyroid cancer (1 paper, 2014). "In the end, we would like to suggest that the overexpression of Wnt4 in thyroid cancer cells is able to revert the mesenchymal phenotype." (PMID 25270402, 2014). "Here, we show that in human thyroid cancer cell lines, Wnt4 and PAX8 mRNA levels are strongly reduced." (PMID 25270402, 2014). "As expected, in all the thyroid cancer cell lines the expression level of Wnt4 is strongly reduced with respect to normal thyroid, indicating that a down-regulation of Wnt4 occurs in thyroid carcinoma." (PMID 25270402, 2014). "Furthermore, we show that a reduced expression of Wnt4 correlates with the alteration of the epithelial phenotype and that Wnt4 overexpression in thyroid cancer cells is able to inhibit cellular migration." (PMID 25270402, 2014). "We analyzed the expression level of Wnt4 in human thyroid cancer cell lines by qRT-PCR." (PMID 25270402, 2014). "Interestingly, we also show that in thyroid cells a reduced expression of Wnt4 correlates with the alteration of the epithelial phenotype and that the overexpression of Wnt4 in thyroid cancer cells is able to inhibit cellular migration." (PMID 25270402, 2014). "Moreover, we also show that the overexpression of Wnt4 in thyroid cancer cells is able to inhibit cellular migration." (PMID 25270402, 2014).
thyroid tumor (1 paper, 2014). A benign or malignant neoplasm affecting the thyroid gland. "To further evaluate the involvement of Wnt4 in thyroid tumors we overexpressed Wnt4 in the BCPAP cell line and we selected a BCPAP-Wnt4 mass population." (PMID 25270402, 2014).
TSHomas (1 paper, 2013). "Previous study had suggested in GHomas and TSHomas a potential activation of non-canonical Wnt/cell polarity pathway, via activation of Erk1/2 MAPK by Wnt4 signaling." (PMID 23638078, 2013).
Turner syndrome (1 paper, 2017). Turner syndrome is a chromosomal disorder associated with the complete or partial absence of an X chromosome. "Included in this group are four genes commonly associated with Turner syndrome (WNT4, MTHFR, FGFR3, and MEN1)." (PMID 28818098, 2017). "We also found evidence that the absence of two X chromosomes leads to overexpression of genes associated with Turner syndrome, including Fgfr3 and Wnt4." (PMID 28818098, 2017).
uremia (1 paper, 2021). A clinical syndrome associated with the retention of renal waste products or uremic toxins in the blood. "The regulation of Wnt/β-catenin such as Wnt1, Wnt4 and β-catenin and PI3K/AKT pathways by adiponectin contributes to the improvement of VC in patients with uremia." (PMID 34398360, 2021).
uterine disorder (1 paper, 2024). A non-neoplastic or neoplastic disorder that affects the uterine corpus or the cervix. "The uterine disorders cluster (two) was significantly associated with six loci, WNT4, GREB1, BSN, SYNE1, GDAP1, and ASTN2." (PMID 39315247, 2024).
uveitis (1 paper, 2018). An inflammatory process affecting a part of or the entire uvea. "Similarly, WNT2B (ENSP00000358698), WNT9A (ENSP00000272164), WNT4 (ENSP00000290167), and WNT2 (ENSP00000265441) all participate in the pathogenesis of uveitis through the regulation of urea cells, thus validating their strong relationships with uveitis." (PMID 30349554, 2018).
vascular occlusion (1 paper, 2018). "Our group previously demonstrated that in a murine model of vascular occlusion, Wnt4 protein expression and β-catenin signalling was upregulated which promoted vascular smooth muscle cell (VSMC) proliferation and intimal thickening." (PMID 29185213, 2018).
vascular occlusive disease (1 paper, 2016). "The Wnt4 gene plays a pivotal role in vascular occlusive disease and our current data suggest that miR-24 may ease this effect by reducing Wnt4 expression." (PMID 27231895, 2016).